DEFB127 (defensin beta 127)
Description:
Has antibacterial activity.
Synonyms: DEFB-27; C20orf73; DEFB27; bA530N10.2; DEF-27; hBD-27
Tractability: Antibody: UniProt places it where antibodies can reach, with high confidence; UniProt predicts a signal peptide or a membrane-spanning region; its Gene Ontology location is reachable by antibodies, with medium confidence.
Gene: Protein-coding gene on chromosome 20 (157,454 to 159,163, forward strand). Ensembl gene ENSG00000088782.
Subcellular location: Secreted
Pathways (Reactome):
Immune System: Beta defensins; Defensins
Gene Ontology:
Molecular function: protein binding
Biological process: antimicrobial humoral immune response mediated by antimicrobial peptide; defense response to Gram-negative bacterium; defense response to bacterium; innate immune response
Cellular component: extracellular region
Genetic constraint (gnomAD): Loss-of-function variants: 2 observed, 3.15 expected, observed/expected ratio (o/e) 0.63, 90% interval 0.25 to 1.7. That is too few expected variants to judge how well the gene tolerates losing a copy. Missense variants: 110 observed, 118.63 expected, observed/expected ratio (o/e) 0.93, 90% interval 0.79 to 1.09. Synonymous variants: 37 observed, 42.04 expected, observed/expected ratio (o/e) 0.88, 90% interval 0.68 to 1.16.
Homologues: Orthologues: chimpanzee DEFB127 (98% identical), macaque DEFB127 (84% identical), pig DEFB127 (67% identical), guinea pig DEFB127 (66% identical), rabbit DEFB127 (60% identical), mouse Defb22 (19% identical), rat Defb22 (15% identical). Paralogues in human: DEFB128 (29% identical), DEFB125 (26% identical), DEFB118 (25% identical), DEFB116 (23% identical), DEFB129 (22% identical), DEFB132 (21% identical), DEFB121 (20% identical), DEFB104A (19% identical), DEFB104B (19% identical), DEFB119 (19% identical), DEFB124 (19% identical), DEFB135 (19% identical), and 7 more.